IL22 (interleukin 22)
Diseases named in the same sentence as IL22 in open-access papers (continued):
Sharing a sentence is not in itself a finding about the gene and the disease.
paracoccidioidomycosis (1 paper, 2021). A systemic fungal infection caused by Paracoccidioides brasiliensis that is most often seen in immunocompromised patients. "Mild or moderate chronic forms of paracoccidioidomycosis are now believed to occur in the context of Th17/Th22 lymphocytes and a mixture of cytokines IL-17 and IL-22 (high levels), IFN-γ, TNF-α, IL-2 and IL-10 and IL-4 (variable levels) and with high levels of IgG1 antibodies." (PMID 33668671, 2021).
periapical granuloma (1 paper, 2016). Chronic nonsuppurative inflammation of periapical tissue resulting from irritation following pulp disease or endodontic treatment. "On estimation of IL-21 levels in periapical granulomas, it was demonstrated that IL-21 along with IL-17A, TNF-α (tumour necrosis factor-α), and IFN-γ were higher in active periapical granulomas, while IL-4, IL-9, IL-10, and IL-22 were higher in inactive periapical granulomas." (PMID 26998377, 2016).
pericarditis (1 paper, 2011). An inflammatory process affecting the pericardium. "Pericardial MMP-9 levels correlated positively with serum and pericardial levels of IL-22 from TB pericarditis patients." (PMID 21767990, 2011). "To investigate whether IL-22 levels may be associated with mediators of lung pathology, we quantified MMP-9 levels in pericardial fluid and matching serum samples from 12 of the 22 TB pericarditis patients." (PMID 21767990, 2011). "IL-22 was undetectable in the pericardial fluid from 24 of 25 control pericarditis patients without TB; 1 control patient had 84 pg/mL of IL-22." (PMID 21767990, 2011).
peritoneal adhesions (1 paper, 2022). "Learning the fact that the formation of peritoneal adhesions might be manipulated by adjusting the expression of IL-22 can be very useful in clinical practice." (PMID 35409053, 2022).
pheochromocytoma (1 paper, 2015). "Supporting these findings, previous studies have shown that IL-22-treated rat pheochromocytoma cells exhibit a modest increased survival in serum-deprived conditions." (PMID 26077779, 2015).
Plasmodium falciparum malaria (1 paper, 2016). Malaria resulting from infection by Plasmodium falciparum. "We could detect high plasma levels of IL-22 in Plasmodium falciparum malaria as well as in Plasmodium berghei ANKA (PbA)-infected C57BL/6J mice." (PMID 27311945, 2016).
pneumococcal meningitis (1 paper, 2014). An acute purulent infection of the meninges and subarachnoid space caused by Streptococcus pneumoniae, most prevalent in children and adults over the age of 60. "This missing difference in brain IL-22 levels argues against a critical role of this TH17-cytokine as a downstream mediator of CCL20/CCR6-induced leukocyte recruitment to the CSF in pneumococcal meningitis." (PMID 24699535, 2014).
proliferative glomerulonephritis (1 paper, 2019). A constellation of renal disorders characterized by an increase number of cells in the glomerulus; these disorders generally present with nephrotic syndrome, and generally progress to end stage renal failure over a matter of weeks to years, depending on the etiology. "Moreover, the mRNA levels of IL-22 were decreased in the urine of LN patients with proliferative glomerulonephritis and inversely correlated with the histological activity index." (PMID 31331400, 2019).
prurigo nodularis (1 paper, 2025). Prurigonodularis (PN) is a skin disease in which hard crusty lumps are formed on the skin that itches intensely. "This speculation is further supported by the significant increase of IL-22 skin expression in NF AD with prurigo nodularis phenotype cohort when compared with the F AD, upon dupilumab treatment." (PMID 40095170, 2025). "Previous studies have emphasized the role of the Th22 subset in patients with prurigo nodularis, where IL-22 enhances keratinocyte proliferation while inhibiting terminal differentiation, leading to epidermal hyperplasia and acanthosis, hallmarks of prurigo nodularis lesions." (PMID 40095170, 2025).
Pseudomonas infection (1 paper, 2016). Infections with bacteria of the genus pseudomonas. "This suggests that IL-22 production can occur as a specific response to pulmonary Pseudomonas infection and that there is migration to and/or expansion of PA-specific IL-22+ producing cells within the thoracic lymph nodes in response to pulmonary infection." (PMID 27375092, 2016). "Interleukin-22 production is evident in patients with CF and pseudomonas infection." (PMID 27375092, 2016).
pulmonary congestion (1 paper, 2022). "IL-22 7.0 [2.0–25.0] vs 6.5 [0.0–18.5] pg/mL, p = 0.18); severity of dyspnea (7.8 ± 2.3 vs 8.0 ± 2.3 points, p = 0.59) and presence of pulmonary congestion (82 vs 89.1%, p = 0.19), respectively." (PMID 36207364, 2022).
renal carcinoma (1 paper, 2015). A carcinoma arising from the epithelium of the renal parenchyma or the renal pelvis. "In renal carcinoma cells, IL-22 suppresses cell growth in a dose dependent manner and inhibits the growth of tumor xenografts; these effects were in part mediated through regulation of STAT1 and ERK1/2 signaling pathways." (PMID 25793261, 2015).
Rickettsiosis (1 paper, 2022). A group of infectious diseases that is caused by Rickettsia. "In a mouse model of TG rickettsiosis, IL-22 seems to support bacterial elimination and thus has protective functions." (PMID 35543881, 2022).
rosacea (1 paper, 2023). A chronic erythematous skin disorder that affects the face. "Thus, several rosacea hallmarks can be directly linked to the killing of dysbiotic commensal bacteria, which initiate type I IFN–driven flare-ups and IL-22–mediated neoangiogenesis, confirming a pathogenic functional role for this pathway in rosacea." (PMID 36633910, 2023). "Furthermore, our findings might provide a basis for the design of therapeutic strategies targeting bacteria subpopulations, pDCs and type I IFN, or IL-22 for the treatment of rosacea and prevention of acute flare-ups." (PMID 36633910, 2023). "In summary, overexpression of cathelicidins induces vascular EC proliferation and neoangiogenesis in rosacea via induction of pDC-derived type I IFN, which in turns leads to upregulation of IL-22 and expression of the IL-22 receptor on ECs, thereby enabling IL-22–driven neoangiogenesis." (PMID 36633910, 2023). "Adaptive T cell–derived cytokines IFNG, IL17A, IL17F, and IL22 were significantly overexpressed in lesional rosacea skin, while IL4 was either undetectable or not increased." (PMID 36633910, 2023).
sacroiliitis (1 paper, 2019). "Some studies found higher IL-22 levels in axial SpA, thus suggesting a possible role in active sacroiliitis." (PMID 31440510, 2019). "It would be interesting to evaluate if there is a correlation between the IL-22 levels and the presence/absence of active sacroiliitis in a larger sample size." (PMID 31440510, 2019). "The current study investigated whether there were differences in ESR, CRP, and some biomarkers (MMP3, IL-17, IL-22, IL-23) in relation to clinical indices of disease activity and the presence/absence of sacroiliitis signs on X-rays and MRIs in an Italian cohort with early and confirmed axSpA." (PMID 31440510, 2019).
salivary gland disorder (1 paper, 2022). A disease involving the saliva-secreting gland. "Hence, endogenously produced IL-22 promotes the development of salivary gland disorder in this T cell-mediated, acute exocrinopathy model." (PMID 36361787, 2022).
small intestinal tumour (1 paper, 2019). "We also observed increased small intestinal tumour burden upon multiple IL-22 injections into young preneoplastic ApcMin/+ mice." (PMID 31770366, 2019).
spondylitis (1 paper, 2019). The inflammation of a vertebra. "On the other hand, significant correlations were found between IL-22 and Bath Ankylosing Spondylitis Functional Index (BASFI), Bath Ankylosing Spondylitis Patient Global Score (BASG1), Health Assessment Questionnaire (HAQ), Visual Analog Scale (VAS pain); MMP3 and mSASSS; MMP3 and hsCRP." (PMID 31440510, 2019).
staphylococcal pneumonia (1 paper, 2022). Pneumonia caused by infections with bacteria of the genus staphylococcus, usually with staphylococcus aureus. "Accordingly, the loss of IL-17 or IL-22 leads to a higher lung bacterial load and severe staphylococcal pneumonia." (PMID 35370996, 2022).
T-cell immunodeficiency (1 paper, 2024). A broad classification of disorders that affect the cell-mediated aspect of the immune response. "This systemic inflammation phenotype is marked by neutrophils and IL-17/IL-22 signaling, does not involve primary T cell immunodeficiency and is independent of bacterial infection." (PMID 38316920, 2024).
T-cell-lymphoma (1 paper, 2021). "Mechanistic studies on PMA/PHA-stimulated T-cell-lymphoma EL-4 cells verified the capability of testosterone/dihydrotestosterone to reduce IL-22 production." (PMID 34638962, 2021).
tetanus (1 paper, 2023). A serious infectious disorder that follows wound contamination by the Gram-positive bacterium Clostridium tetani. "At the early post-immunizations time point, APRIL and IL-22 were positively associated with 12-month tetanus IgG levels, while plasmablasts were negatively associated." (PMID 37251388, 2023).
thyroid-associated ophthalmopathy (1 paper, 2017). "We further analyzed the allele and genotype frequencies of IL-22 SNPs with ophthalmopathy in AITD patients, and this study demonstrated that the SNP rs11611206 within the IL-22 gene was associated with thyroid-associated ophthalmopathy (TAO) (P = 0.023)." (PMID 28839453, 2017).
tick-borne encephalitis (1 paper, 2018). Tick-borne encephalitis is caused by an arbovirus of the Flaviviridae family (tick-borne encephalitis virus, TBEV), transmitted principally by the bite of the Ixodes ricinus tick. "Concentrations of IL-17A, IL-17F, IL-22, CXCL1, and CXCL2 in serum (S) samples obtained from tick-borne encephalitis patients on admission to hospital are shown horizontal axes and in cerebrospinal fluid (CSF) samples obtained simultaneously on vertical axes (expressed in pg/ml)." (PMID 29678185, 2018).
toxoplasmosis (1 paper, 2015). A parasitic disease contracted by the ingestion or fetal transmission of toxoplasma gondii. "Since IL-22 has been shown to promote tissue pathology during toxoplasmosis, it was unexpected that Ahr-/- mice with a marked defect in IL-22-producing RORγt+ ILCs would develop increased intestinal pathology." (PMID 26010337, 2015). "Group 3 ILCs in naive mice expressed IL-22, and this was not significantly altered during toxoplasmosis." (PMID 26010337, 2015).
ulcer (1 paper, 2022). "Conversely, recombinant IL-22, F-652 or UTTR1147A, might strengthen its protective role in IL-22-deficient diseases such as GVHD and ulcer." (PMID 35911703, 2022).
uremia (1 paper, 2018). A clinical syndrome associated with the retention of renal waste products or uremic toxins in the blood. "Unfortunately, the UUO model does not allow for the assessment of systemic effects of uremia and the role of IL‐22 in this context." (PMID 30156011, 2018).
xerostomia (1 paper, 2015). Dryness of the mouth resulting from reduced salivary secretion. "Circulating IL22 was significantly elevated in pSS and showed significant correlations with major characteristics such as xerostomia, anti-SSB, rheumatoid factor, and hypergammaglobulinemia." (PMID 26436101, 2015).
yersiniosis (1 paper, 2019). "The IL-22 producing cells induced by bacterial infection was also examined in another important salmonid disease model, yersiniosis caused by Y. ruckeri, in a separate experiment." (PMID 31306696, 2019).
infection (522 papers, 2009 to 2026). The state of being infected such as from the introduction of a foreign agent such as serum, vaccine, antigenic substance or organism. "Infection increased the abundance of an enterocyte subtype with high expression of defense-associated functions and stimulated production of IL22, a cytokine linked to epithelial integrity, from group 3 innate lymphoid cells." (PMID 41959413, 2026). "Infection increased the abundance of an enterocyte subtype with high expression of defence-associated functions and stimulated production of IL-22, a cytokine linked to epithelial integrity, from group 3 innate lymphoid cells." (PMID 42236988, 2026). "In the established phase of COPD, an impaired IL-22 response facilitates pathogen-associated infections and disease exacerbations." (PMID 41409289, 2025). "IRF4-deficient mice exhibit reduced NKp46+ ILC3s, expanded precursor-like NKp46−CCR6− ILC3s, and impaired interleukin-22 (IL-22)/IL-17A production, increasing susceptibility to infections." (PMID 40585371, 2025). "Studies have shown that IL-22-deficient mice exhibit exacerbated intestinal inflammation and epithelial barrier damage leading to generalized infection." (PMID 40568578, 2025). "In this study, downregulated genes in the field infection group distinctly suppressed T cell activation pathways, while the vaccine strain distinctly upregulated IL-22 encoding genes and downregulated genes involved in IFN-γ signalling pathways." (PMID 41435987, 2025). "ICA promotes the secretion of IL‐22 by ILC3s by targeting Rorγt, thereby improving the intestinal barrier and reducing susceptibility to infections." (PMID 40236767, 2025). "This conclusion is consistent with the observation that chlamydial mutant organisms were detected in the large intestines of IL-22-deficient mice for at least 56 days post-infection." (PMID 41040885, 2025). "Accordingly, global IFNLR1-/- mice had significantly increased IL-17 and IL-22 in the airways, and neutralization of IL-17A during infection caused significantly increased bacterial burden compared to untreated mice." (PMID 39178311, 2024). "Our study demonstrates, using an experimental mice model that the in vivo infection caused by R265 indeed results in a significant accumulation of IL-22 in both the lungs and brain of infected animals." (PMID 39635124, 2024). "Consistent to previously reported, CR infection in SPF Il22-/- mice resulted in severe body weight loss, watery diarrhea, and 100% mortality by 14 days post inoculation (dpi)." (PMID 39630719, 2024). "Supplementation of IL-18 into IL-22 deficient mice restored mucin secretion, indicating that IL-22 acted upstream of IL-18 secretion during infection." (PMID 39428744, 2024). "Our IL-22 treatment regimen caused a significant increase in IL-22 protein levels within the colon prior to infection." (PMID 39349385, 2024). "The IL-22−/− mice displayed a prominent weight loss in the late days of infection when compared with the WT infected group." (PMID 39635124, 2024). "In contrast, IL-18 and IL-22 independent signaling through Nlrp6 underlies only a modest, infection-induced increase in mucin secretion from goblet cells in the distal colon." (PMID 39428744, 2024). "The experimental results indicate that STM infection in the mouse intestine causes severe intestinal damage and endangers the lives of the mice, with higher levels of IL-22 being secreted in the intestine." (PMID 39080852, 2024). "Under GF condition, infection of CR in both Rag1-/- and Il22-/- mice is sufficient to cause severe symptoms and mortality, supporting that CR indeed harbors gut microbiota-independent virulence." (PMID 39630719, 2024). "To investigate the impact of IL-22 and IL-23, we evaluated the knockout mice susceptibility to infection." (PMID 39635124, 2024). "In the case of IL-22, this cytokine has also been associated with a protective function during ST infection but has recently been shown to aggravate the infection in some cases." (PMID 38542999, 2024).
infection (continued). "The AUROC (95%CI) was significantly higher for IL-17 than IL-22 (0.829 (0.732–0.902) vs. 0.504 (0.393–0.614), p < 0.001), suggesting that IL-17 has a stronger correlation with infection risk than IL-22." (PMID 38273234, 2024). "IL-22 impacts not only pathogenic bacteria to prevent infection, but also commensal gut microbiota to orchestrate microbial symbiosis." (PMID 37908362, 2023). "Other potential explanations include γδ T cell production of antimicrobial peptides, IL-22, and neutrophil recruiting chemokines to promote host survival, which have been associated with protection against S. aureus at other infection sites." (PMID 37483624, 2023). "Compared to the wild-type group, IL-22-deficient mice showed increased mortality after infection with C. difficile." (PMID 36839448, 2023). "For example, in HIV infection, it is observed that the increased amounts of Th22 cells are associated with resistance to infection and IL-22 has a protective role in mucosal sites." (PMID 37403036, 2023). "The microbiota-derived metabolites can activate TLR2 on glial cells, which results in an increased IL-22 secretion by innate lymphoid cells (ILC)-3 to provide protection against inflammation or pathogenic infection." (PMID 35626706, 2022). "The proinflammatory cytokines IL-22 and IL-17 are produced from the early phases of infection (5, 22, –, 24), and IL-22-deficient mice suffer from leaky gut, leading to systemic bacterial dissemination and fatality." (PMID 35100877, 2022). "For example, Ahr is a critical regulator for adult ILC3 development and IL-22 production, and therefore, the Ahr-deficient mice are more prone to infections." (PMID 35163778, 2022). "Nevertheless, these ThPOK-deficient mice showed similar percentages of IL-22-producing ILC3s during infection." (PMID 35844574, 2022). "This loss of ILC3s renders the mice more susceptible to CR infection, as simultaneously to the reduced amount of ILC3s, less IL-22 and antimicrobial peptides, important for pathogen defense, are produced." (PMID 36430676, 2022). "AhR deficiency has been related to a decrease in IL-22 levels and therefore susceptibility to infections." (PMID 35742682, 2022). "This susceptibility to infection involves a defective production of interleukin (IL)-22 which plays an important role in mucosal defense." (PMID 33784296, 2021). "As transcripts encoding IL-22 were increased in lymph ILCs during infection, we assessed the cytokine profile of migratory ILCs." (PMID 33414524, 2021). "The increased susceptibility to infection during COPD is linked to a defect in IL-22 production related with an altered innate immune response." (PMID 33784296, 2021). "As for the major cytokines produced by ILC3s, IL-17, and IL-22 are mainly reported as protective effectors in host defense during infections, whereas proinflammatory and pathogenic effects tend to dominate in non-infectious inflammation." (PMID 33718260, 2021). "In this context, Il22−/− mice have normal susceptibility to infection but have higher bacterial burden in the lungs during the chronic stage." (PMID 33692792, 2021). "Significantly, IL-22-deficient mice developed a more severe infection, resulting in a higher mortality rate, an increased viral titer and exacerbated liver injury than their wild-type counterparts." (PMID 33851257, 2021). "In experimental P. chabaudi malaria infection in mice, a higher production of IL-22 was observed in the liver, which is important as it suggests that this cytokine is an essential factor in the protection against the lethal infection caused by P. chabaudi." (PMID 32148440, 2020). "Seven days after infection, IL-22 deficiency also culminated in a reduction in IFN-γ or IL-17-producing CD4+ T cells in the lungs." (PMID 32517114, 2020). "Further verification using q-PCR indicated that IL6 and IL22 expression levels were unchanged during PmCQ2 infection, which implies that PmCQ2 causes a lower inflammatory response." (PMID 32851030, 2020).